SKP2 (S-phase kinase associated protein 2)
Diseases named in the same sentence as SKP2 in open-access papers (continued):
Sharing a sentence is not in itself a finding about the gene and the disease.
glioblastoma (18 papers, 2012 to 2025). The most malignant astrocytic tumor (WHO grade IV). "For example, another study demonstrated that the signal transducer and activator of the transcription Skp2/p27 pathway was associated with senescence in glioblastoma cells." (PMID 37779163, 2023). "Indeed, the first FBP described, Skp2 (S-phase kinase-associated protein 2, Fbxl1) is activated by amplification in several cancers, including breast, lymphoma, non-small cell lung cancer and glioblastoma." (PMID 31560077, 2020). "For instance, ADAR2 targets intronic Alu elements of phosphatase cell division cycle 14B (CDC14B), an upstream regulator of S-phase kinase-associated protein 2 (Skp2)/p21/p27 pathway, in glioblastoma (GBM)." (PMID 39126156, 2025). "Indeed, down-regulation of Skp2 caused cell growth arrest and apoptosis in T98G glioblastoma cells." (PMID 26046466, 2015). "Through the targeting of Skp2, RA impedes the proliferation, migration, and invasion of glioblastoma cells, and also proficiently counteracts EMT processes and reduces stemness attributes." (PMID 39744562, 2025). "Studies suppressing Skp2 expression have led to decreased malignant cell proliferation and tumorigenesis, as well as increased sensitivity of glioblastoma cells to TMZ." (PMID 39744562, 2025). "The results indicated that in both glioblastoma cell lines, RA downregulated Skp2 in mRNA level and RA suppressed levels of Skp2 protein and EMT-associated proteins in a dose-dependent manner." (PMID 39744562, 2025). "Our findings align with these observations, highlighting Skp2 as a promising target in glioblastoma treatment, with RA showing efficacy in reducing Skp2-mediated malignancy traits." (PMID 39744562, 2025). "In particular, the correlation between NUCKS1 and SKP2 is most striking in glioblastoma, kidney renal papillary cell carcinoma, skin cutaneous melanoma, and uveal melanoma." (PMID 34845229, 2021). "To further clarify the effect of Skp2 on glioma cell proliferation, we suppressed its level in glioblastoma (GBM) cell lines through knockdown and small molecule inhibitors (lovastatin and SZL-P1-41)." (PMID 32165861, 2020). "In this study, our results indicated that compound-7g suppresses cell cycle at G1 phase by promoting SKP2 decrease and p27 accumulation, suggesting that SKP2 induced p27 degradation is inhibited by compound-7g in glioblastoma cells." (PMID 31357480, 2019). "It has been reported that butylidenephthalide, isolated from Angelica sinensis, down-regulated Skp2 expression and subsequently increased p16 and p21 expressions, leading to cell senescence in human glioblastoma multiform." (PMID 26046466, 2015). "One study has shown that FoxM1 (Forkhead box protein M1) activated the expression of Skp2 in glioblastoma." (PMID 26046466, 2015). "We also provided the first evidence that BMPR-IB inhibits the growth of glioblastoma cells and promotes their differentiation by regulating the gene expression of p21, p27Kip1 and Skp2, which plays important roles in cell cycle regulation." (PMID 22650359, 2012). "This suggests that RA targets Skp2 in its suppression of EMT in glioblastoma cells." (PMID 39744562, 2025). "In glioblastoma, elevated Skp2 expression correlates with poorer survival and prognosis." (PMID 39744562, 2025). "Our study suggests that NSC139021 may be a potential chemotherapy drug for the treatment of glioblastoma by targeting the Skp2-p27/p21-Cyclin E/CDK2-pRb signaling pathway." (PMID 34572430, 2021). "Thus, compound-7g may function as an inhibitor in both CRC and glioblastoma cells by down-regulating SKP2." (PMID 31357480, 2019). "Therefore, identifying compounds that downregulate SKP2 by inhibiting protein content of E2F transcriptional factor might be an effective strategy for cancer therapy such as glioblastoma." (PMID 31357480, 2019).
glioblastoma (continued). "Moreover, we recently demonstrated that ADAR2 deaminase activity is sufficient to inhibit glioblastoma proliferation and tumor growth, as it modulates the CDC14B/Skp2/p21/p27 pathway in adult glioblastoma cell lines and this was further confirmed in different grades of pediatric glioma." (PMID 25582055, 2015). "Additionally, oncostatin M has been found to inhibit the Skp2 levels in glioblastoma cells." (PMID 26046466, 2015). "In our study, we demonstrated RA inhibited migration and invasion via downregulation of Skp2-induced EMT, further confirming the efficacy of RA in targeting EMT for the treatment of glioblastoma." (PMID 39744562, 2025). "PTEN depletion causes a decrease in p27Kip1 levels with concomitant increase in Skp2, whereas ectopic PTEN expression leads to p27Kip1 accumulation, which is accompanied by a decrease of Skp2 in human glioblastoma cells." (PMID 32313103, 2020). "Notably, the augmentation of Skp2 expression diminished RA's suppressive impact on the invasion, migration, proliferation of glioblastoma cells, and the expression of EMT indicators RT-PCR further confirmed that RA reduced Skp2 mRNA levels." (PMID 39744562, 2025). "For example, Skp2 was diffusely or focally expressed in most glioblastomas, whereas Skp2 expression was absent or very low in well differentiated astrocytomas." (PMID 26046466, 2015). "Furthermore, the overexpression of WT-STAT3, but not non-phosphorylated STAT3, rescued glioblastoma cells from the induction of senescence combined with a restoration of SKP2 expression levels." (PMID 25412315, 2014). "Particularly, SKP2 expression had a remarkable capacity to differentiate eight cancers from their control tissues; the eight neoplasms were BLCA, CESC, COAD, ESCA (esophageal carcinoma), GBM (glioblastoma multiforme), LUSC, PCPG (pheochromocytoma and paraganglioma), and READ (AUC > 0.90)." (PMID 37308972, 2023).
lymphoma (18 papers, 2008 to 2024). A malignant (clonal) proliferation of B- lymphocytes or T- lymphocytes which involves the lymph nodes, bone marrow and/or extranodal sites. "The SKP2 gene encodes a member of the F-box protein family, this gene is established as a protooncogene involved in the pathogenesis of lymphomas." (PMID 37185598, 2023). "Conversely, SKP2 overexpression results in rapid cell cycle entry and is frequently associated with poor prognosis in cancers, including leukemia and lymphoma." (PMID 31772299, 2020). "SKP2 upregulation results in rapid cell cycle entry and is frequently associated with poor prognosis in cancers, including leukemia and lymphomas." (PMID 31772299, 2020). "Results depict that leukemia showed a marginally increased trend in Skp2 expression as compared to lymphoma and Myeloma." (PMID 38559562, 2024). "Survival analysis also revealed a poor DFS (disease-free survival) with high Skp2 expression, as also seen in leukemia vs lymphoma." (PMID 38559562, 2024). "The function of Cks1 and Skp2 in lymphoma development is however not clearly understood as the correlative data from several studies indicates that sole accumulation of p27Kip1 is not the mechanistic explanation for the observed effects." (PMID 22624029, 2012). "In one report, overexpression of Skp2 in the mouse prostate induced hyperplasia, dysplasia and low-grade carcinoma, while others have reported that Skp2 transgenic mice co-expressing N-Ras develop lymphomas." (PMID 19549334, 2009). "Lwin and colleagues previously reported that adhesion of lymphoma cell lines to BMSCs causes the cells to enter a protected quiescent state, mediated through upregulation of Fzr, leading to degradation of APC/CFzr substrate Skp2 and an accumulation of p27." (PMID 27655696, 2016).
pancreatic cancer (18 papers, 2008 to 2024). "CUR treatment leads to a decrease in the accretion of S-phase kinase-associated protein 2 (S-phase Skp2) and enhances p27 protein accumulation in the pancreatic cancer cell, resulting in a significant amelioration of diabetic nephropathy." (PMID 34833928, 2021). "Furthermore, the expression of SKP2 was negatively associated with p27 which was similar to the results of previous studies in pancreatic cancer." (PMID 28193232, 2017). "In aggregate, these results demonstrate that the FoxO3a-Skp2-p27Kip1 pathway, first defined by our in vitro mechanistic experiments in cultured pancreatic cancer cells, associates with the Nupr1−/− genotype in vivo giving rise to OIS with a concomitant impairment in PanIN development." (PMID 24902898, 2014). "Taken together, the results indicate that Mint3 promotes SKP2 expression, thereby decreasing p21/p27 protein levels and enhancing cell proliferation in pancreatic cancer cells during normoxia." (PMID 32826949, 2020). "Nevertheless, we cannot exclude the possibility that HIF-1 target genes other than SKP2 also contribute to the Mint3-dependent tumorigenicity of pancreatic cancer." (PMID 32826949, 2020). "Altogether, these findings indicate that Mint3-mediated SKP2 expression and enhanced cell proliferation in pancreatic cancer cells are dependent on FIH-1 activity." (PMID 32826949, 2020). "We further analyzed Mint3 expression in public clinical datasets and tissue microarrays of pancreatic cancer and found that Mint3 expression is positively correlated with SKP2 expression at mRNA and protein levels." (PMID 32826949, 2020). "In pancreatic cancer, high SKP2 expression is correlated with poor prognosis, which is consistent with our database analysis of Mint3 expression in pancreatic cancer." (PMID 32826949, 2020). "Here, we showed that HIF-1 activity during normoxia is maintained by Mint3 and that Mint3 depletion attenuates SKP2 expression via HIF-1 in pancreatic cancer cells." (PMID 32826949, 2020). "Mint3 depletion further affects tumor malignancy by attenuating cell proliferation, partial EMT, and chemoresistance in pancreatic cancer cells in vitro via decreased SKP2 expression." (PMID 32826949, 2020). "Further analyses revealed that Mint3 increased transcription of the oncogenic ubiquitin ligase SKP2 in pancreatic cancer cells via HIF-1." (PMID 32826949, 2020). "Database and tissue microarray analyses showed that Mint3 expression is correlated with SKP2 expression in human pancreatic cancer specimens and high Mint3 expression is correlated with poor prognosis of pancreatic cancer patients." (PMID 32826949, 2020). "In our previous report, we have shown that ATO inhibited cell growth and invasion via downregulation of Skp2 in pancreatic cancer (PC) cells." (PMID 30847385, 2019). "Data on human tumours demonstrate that p27Kip1 expression is inversely correlated to Jab1 expression, and recently Jab1 expression has been demonstrated to induce p27Kip1 degradation by a Skp2 independent mechanism in pancreatic carcinoma cells." (PMID 18474118, 2008). "Recently Jab1 expression, inversely correlated to p27Kip1 expression in pancreatic carcinoma and has been demonstrated to induce p27Kip1 degradation by a Skp2-independent mechanism." (PMID 18474118, 2008). "Although Mint3 depletion attenuates SKP2 expression in pancreatic cancer cells, whether this regulation is specific to cancer cells remains unclear." (PMID 32826949, 2020). "Thus, the Mint3/FIH-1/HIF-1α axis increases SKP2 mRNA levels, at least in part, by enhancing the promoter activity of SKP2 in pancreatic cancer cells." (PMID 32826949, 2020). "Mint3 depletion attenuated HIF-1 activity in pancreatic cancer cells, but whether Mint3-mediated SKP2 expression and enhanced cell proliferation rely on the Mint3-FIH-1-HIF-1 axis remained unclear." (PMID 32826949, 2020). "Interestingly, SKP2 mRNA and protein levels were decreased in Mint3-depleted pancreatic cancer cells." (PMID 32826949, 2020).
pancreatic cancer (continued). "Next, we examined whether the increased p21/p27 levels and attenuated cell proliferation induced by Mint3 depletion depend on SKP2 in pancreatic cancer cells." (PMID 32826949, 2020). "Because SKP2 expression levels oscillate during the cell cycle, decreased SKP2 may result from the altered distribution of cell cycle phases in Mint3-depleted pancreatic cancer cells." (PMID 32826949, 2020). "Further studies are needed to clarify whether and how genetic/epigenetic regulations allow Mint3/HIF-1 to induce SKP2 expression specifically in pancreatic cancer during carcinogenesis." (PMID 32826949, 2020). "Mint3 depletion attenuates SKP2 expression via HIF-1 in pancreatic cancer cells." (PMID 32826949, 2020). "Subsequently, whether overwhelming Mint3 by FIH-1 overexpression affects SKP2 expression and cell proliferation in pancreatic cancer cells was examined using the Tet-on expression system." (PMID 32826949, 2020). "The inhibitory effect of IATL on both EGF and SKP2 may offer a novel option for pancreatic cancer." (PMID 33661942, 2021). "Furthermore, IATL inhibits pancreatic cancer cell proliferation by AMPK- Skp2-Akt signal pathway." (PMID 33661942, 2021). "We found that Mint3 depletion decreased the expression of the S-phase kinase associated protein (SKP2) oncogene via HIF-1 during normoxia, thereby attenuating malignant features such as cell proliferation, stemness, chemoresistance, and tumorigenicity in pancreatic cancer cells." (PMID 32826949, 2020). "Thus, Mint3-mediated SKP2 expression is specific to pancreatic cancer cells." (PMID 32826949, 2020). "Among the tested EMT-related proteins, Mint3 depletion decreased Slug levels in pancreatic cancer cells in a HIF-1α- and SKP2-dependent manner." (PMID 32826949, 2020). "H6c7 cells expressed Mint3 at a comparable level to pancreatic cancer cells; however, Mint3 depletion did not affect SKP2 expression in H6c7 cells." (PMID 32826949, 2020). "Expression of WT Mint3, but not MUT Mint3, increased SKP2, decreased p21 and p27 protein levels, and restored cell proliferation in Mint3-KD pancreatic cancer cells." (PMID 32826949, 2020). "As Mint3 controlled SKP2 mRNA levels in pancreatic cancer cells via FIH-1, we further examined whether Mint3-mediated SKP2 expression depends on HIF-1." (PMID 32826949, 2020). "Interestingly, although H6c7 cells expressed Mint3 at a comparable level to pancreatic cancer cells, Mint3 depletion did not affect SKP2 expression in H6c7 cells." (PMID 32826949, 2020). "Thus, inflammation and/or other factors in the tumor microenvironment may affect both Mint3 and HIF-1α expression in pancreatic cancer, and co-overexpressed Mint3 and HIF-1α might further induce SKP2 overexpression and thereby promote pancreatic cancer progression." (PMID 32826949, 2020).
non-small cell lung carcinoma (17 papers, 2006 to 2026). A group of at least three distinct histological types of lung cancer, including non-small cell squamous cell carcinoma, adenocarcinoma, and large cell carcinoma. "Research has shown that several downstream targets of FOXM1, including survivin, cyclin B1, S-Phase Kinase-Associated Protein 2, and CDC25B, were significantly upregulated in non-small-cell lung cancer cells treated with gefitinib." (PMID 37242455, 2023). "Such as miR-1297 promotes the proliferation of non-small cell lung cancer cells by participating in the PTEN/Akt/Skp2 signaling pathway." (PMID 38095636, 2023). "Four neuroblastoma xenograft samples derived from cell lines with known N-myc gene copy number were also evaluated, as were 7 samples of non-small cell lung cancer (NSCLC) tumors with known Skp2 gene amplification." (PMID 17156491, 2006). "Given that EGF activates AMPK to drive Skp2-mediated ubiquitination and activation of Akt, we next examined whether the AMPK-Skp2-Akt axis contributes to the resistance to EGFR targeting therapy in non-small cell lung cancer cells (NSCLC)." (PMID 30413706, 2018). "SIRT2 inhibits non-small cell lung cancer cell growth through impairing Skp2-mediated p27." (PMID 28514749, 2017). "In addition, SIRT2 induces Skp2 deacetylation and subsequent degradation, then promoting p27 protein level in non-small cell lung cancer." (PMID 27794562, 2016). "It has been demonstrated to bind to Skp2 by forming H-bonds with the Lys145 residue, decreasing Skp2 stability, preventing Skp1-Skp2 interaction and thus inhibiting SCFSkp2 E3 ligase, leading to decreased tumor proliferation and migration in non-small-cell lung cancer." (PMID 37089937, 2023). "Skp2 S256 phosphorylation by AMPK promotes Skp2-SCF complex formation enhancing its E3 ligase activation, which leads to K63-ubiquitination and activation of Akt, and finally contributing to a resistance to EGFR targeting therapy, such as Gefitinib, in non-small cell lung cancer cells (NSCLC)." (PMID 34068643, 2021).